CNTD1 (cyclin N-terminal domain containing 1)
Description:
Plays a role in the different steps of crossover formation during meiotic recombination. Participates in the crossover differentiation step of crossover-specific recombination intermediates through its interaction with PRR19. In addition, stimulates crossover formation through the interactions with RFC3 and RFC4 and simultaneously regulates cell-cycle progression through interactions with CDC34 and subsequent ubiquitination of WEE1. May also participates in an active deselection process that destabilizes or removes excess pre-CO intermediates.
Synonyms: CNTD; FLJ40137; COSA1
Tractability: No criterion of Open Targets' tractability assessment is met for any kind of drug.
Gene: Protein-coding gene on chromosome 17 (42,798,800 to 42,811,587, forward strand). Ensembl gene ENSG00000176563.
Subcellular location: Nucleus; Cytoplasm; Chromosome
Subcellular location (Human Protein Atlas): Nucleoplasm; Vesicles
Gene Ontology:
Biological process: reciprocal meiotic recombination; regulation of meiotic cell cycle
Cellular component: chromosome; cytoplasm; nucleus; site of double-strand break
Genetic constraint (gnomAD): Loss-of-function variants: 13 observed, 33.5 expected, observed/expected ratio (o/e) 0.39, 90% interval 0.25 to 0.62. The synonymous counts are far from expectation, so gnomAD's model fits this gene poorly and the ratio says little. Missense variants: 327 observed, 392.33 expected, observed/expected ratio (o/e) 0.83, 90% interval 0.76 to 0.91. Synonymous variants: 123 observed, 158.72 expected, observed/expected ratio (o/e) 0.77, 90% interval 0.67 to 0.9.
Homologues: Orthologues: chimpanzee CNTD1 (99% identical), macaque CNTD1 (96% identical), dog CNTD1 (85% identical), mouse Cntd1 (85% identical), pig CNTD1 (85% identical), rabbit CNTD1 (82% identical), guinea pig CNTD1 (73% identical), tropical clawed frog CNTD1 (42% identical), Caenorhabditis elegans cosa-1 (20% identical).
Diseases named in the same sentence as CNTD1 in open-access papers:
CNTD1 is named in the same sentence as 4 diseases in open-access papers, as found by Europe PMC text mining. Sharing a sentence is not in itself a finding about the gene and the disease. The quoted sentences say what the papers report.
tumor (2 papers, 2017 to 2018). "Expression of CNTD1, CNTD2 CCNG2, or SPY1 was undetectable in the tumor or normal cells." (PMID 28860486, 2017).
CNTD1 also shares sentences with these, for which no sentence is quoted: colorectal cancer (1 paper); lung adenocarcinoma (1); lung carcinoma (1).